IGHV2-5 (immunoglobulin heavy variable 2-5)
Description:
V region of the variable domain of immunoglobulin heavy chains that participates in the antigen recognition. Immunoglobulins, also known as antibodies, are membrane-bound or secreted glycoproteins produced by B lymphocytes. In the recognition phase of humoral immunity, the membrane-bound immunoglobulins serve as receptors which, upon binding of a specific antigen, trigger the clonal expansion and differentiation of B lymphocytes into immunoglobulins-secreting plasma cells. Secreted immunoglobulins mediate the effector phase of humoral immunity, which results in the elimination of bound antigens. The antigen binding site is formed by the variable domain of one heavy chain, together with that of its associated light chain. Thus, each immunoglobulin has two antigen binding sites with remarkable affinity for a particular antigen. The variable domains are assembled by a process called V-(D)-J rearrangement and can then be subjected to somatic hypermutations which, after exposure to antigen and selection, allow affinity maturation for a particular antigen.
Synonyms: IGHV25; VH
Tractability: Antibody: its Gene Ontology location is reachable by antibodies, with high confidence; UniProt places it where antibodies can reach, with medium confidence; UniProt predicts a signal peptide or a membrane-spanning region.
Gene: Immunoglobulin variable (V) gene on chromosome 14 (106,037,902 to 106,038,365, reverse strand). Ensembl gene ENSG00000211937.
Subcellular location: Secreted; Cell membrane
Pathways (Reactome):
Immune System: Antigen activates B Cell Receptor (BCR) leading to generation of second messengers; CD22 mediated BCR regulation; Classical antibody-mediated complement activation; FCERI mediated Ca+2 mobilization; FCERI mediated MAPK activation; FCERI mediated NF-kB activation; FCGR activation; Fc epsilon receptor (FCERI) signaling; Immunoregulatory interactions between a Lymphoid and a non-Lymphoid cell; Initial triggering of complement; Regulation of Complement cascade; Regulation of actin dynamics for phagocytic cup formation; Role of LAT2/NTAL/LAB on calcium mobilization; Role of phospholipids in phagocytosis
Disease: FCGR3A-mediated IL10 synthesis; FCGR3A-mediated phagocytosis; Potential therapeutics for SARS
Hemostasis: Cell surface interactions at the vascular wall
Vesicle-mediated transport: Scavenging of heme from plasma
Gene Ontology:
Molecular function: antigen binding
Biological process: immune response; immunoglobulin mediated immune response
Cellular component: extracellular region; plasma membrane
Homologues: Orthologues: mouse Ighv8-12 (72% identical), mouse Ighv8-6 (70% identical), mouse Ighv8-8 (70% identical), mouse Ighv8-9 (69% identical), mouse Ighv8-5 (68% identical), mouse Ighv8-4 (66% identical), rat AABR07065813.1 (66% identical), mouse Ighv8-11 (65% identical), mouse Ighv8-13 (62% identical), mouse Ighv8-2 (61% identical), rat Igh-6-ps1 (54% identical). Paralogues in human: IGHV2-70 (87% identical), IGHV2-70D (87% identical), IGHV2OR16-5 (82% identical), IGHV2-26 (82% identical), IGHV4-39 (56% identical), IGHV4-28 (55% identical), IGHV4-59 (55% identical), IGHV4-61 (55% identical), IGHV4-31 (54% identical), IGHV4-4 (52% identical), IGHV4OR15-8 (51% identical), IGHV4-34 (50% identical), and 65 more.